IL6 (interleukin 6)
Diseases named in the same sentence as IL6 in open-access papers (continued):
Sharing a sentence is not in itself a finding about the gene and the disease.
COVID-19 (continued). "When the cytokine profile in diabetes was analyzed in relation to COVID-19, the focus was again on IL-6, which was reported to play a more deleterious role in COVID-19 infection." (PMID 32733487, 2020). "Foremost among the potential physiological connections related to the present discussion is the so-called ‘cytokine storm’ mediated by interleukin-6 (IL-6) reported in some COVID-19 patients." (PMID 33066821, 2020). "There was considerable variation in plasma IL-6 levels in COVID-19 patients, with a range from 6 to more than 5000 pg/μL." (PMID 32687484, 2020). "As previously reported, we found high levels of acute-phase inflammatory cytokine IL-6, targeted by tocilizumab in COVID-19 patient treatments." (PMID 33239683, 2020). "Direct comparisons in the literature of clinical observations in COVID-19 patients with IL-6 induced “cytokine storm” or cytokine release syndrome (CRS) should be made with caution." (PMID 33013871, 2020). "Our study showed that TNF-α is a potent cytokine related to pathological inflammation in tissues—similar to IL-6—in patients with COVID-19." (PMID 33424804, 2020). "As expected, maximal plasma IL-6 levels were significantly elevated in COVID-19 patients with high PCT levels compared to patients with low PCT levels." (PMID 32917983, 2020). "Anti-malarial drugs hydroxychloroquine and chloroquine that are know to decrease Th17-related cytokines; IL-6, IL-17, IL-22, TNFα and IL-1β have been evaluated for efficacy in COVID-19 treatment in several clinical trials." (PMID 33708109, 2020). "Because of the prominent role of IL-6 in COVID-19, it was the first drug proposed for the treatment of the inflammatory complications in patients with severe disease." (PMID 33033405, 2020). "They demonstrated that HCQ was capable of mimicking the influential properties of anti-IL-6 antibody by significantly decreasing the concentrations of IL-6 in the critically ill COVID-19 patients." (PMID 33062720, 2020). "In particular, the serum level of IL-6 is significantly increased in severely ill COVID-19 patients, inducing the administration of TCZ in patients." (PMID 32967358, 2020). "It has been demonstrated that elevated serum levels of IL-6 and CRP as inflammatory markers are associated with the severity of COVID-19 and can be used as a predictive factor for disease risk." (PMID 32943404, 2020). "Several other reports have also confirmed increasing IL-6 levels among critically ill COVID-19 patients." (PMID 32948252, 2020). "In analogy to patients infected with SARS-CoV or MERS-CoV, CD4 Th1-cells expressing GM-CSF, and IL-6 were isolated from patients with COVID-19 CRS." (PMID 33154972, 2020). "Only IL-6 significantly changed over time between the two groups (p = 0.003), observing more stable levels of IL-6 during COVID-19 in patients with headache." (PMID 33146036, 2020). "Early data has revealed that IL-6, a key regulatory cytokine, plays an important role in the cytokine storm of COVID-19." (PMID 33469465, 2020). "Severe hospitalized COVID-19 patients overexpressed pro-inflammatory cytokines (i.e., IL-1 beta, IL-2, IL-6, IL-17, TNFα)." (PMID 33019628, 2020). "Several cohort studies reported that markedly elevated serum IL-6 levels in the 100–10,000 pg/mL range in severe COVID-19 patients." (PMID 33233531, 2020). "IL-6 trans-signaling mediates inflammation leading to cardiovascular diseases that is a complication in COVID-19 patients." (PMID 33195318, 2020). "Different papers have demonstrated a correlation between high serum IL-6 levels and adverse clinical outcomes in patients with COVID-19." (PMID 33292350, 2020). "Inhibiting interleukin-6 (IL-6), whose secretion leads to an overactive immune response, improves the treatment of severe COVID-19 patients by avoiding cytokine release syndrome (CRS)." (PMID 33574756, 2020).
COVID-19 (continued). "A comparative study of patients with severe and mild COVID-19 demonstrated that all cytokines, except IL-6 and IL-10, reached their peak serum levels 3-6 days after disease onset." (PMID 32792851, 2020). "Research outcomes for these studies are expected to fill the knowledge gap in the treatment efficacy of IL-6 inhibitors for patients with COVID-19." (PMID 33364959, 2020). "This is in contrast to 6 deaths (18%) noted among 34 similar patients who received treatment for COVID-19 in our medical ICU around the same time (notably all patients were treated with anti-IL6 therapy)." (PMID 32399655, 2020). "Blood levels of the prototypic acute phase reactant, C-reactive protein (CRP), which is hepatically synthesized and released in response to interleukin-6 stimulation, is markedly elevated in patients with COVID-19." (PMID 32588812, 2020). "Most severely ill COVID-19 patients manifest a hyperactivated immune response, instigated by interleukin 6 (IL6) that triggers a so called “cytokine storm” and coagulopathy." (PMID 32826388, 2020). "In this study, we found that COVID-19 patients with elevated IL-6 levels had a higher likelihood of experiencing renal, hepatic, and lung injuries." (PMID 32765283, 2020). "Patients with a severe course of COVID-19 had significantly increased interleukin (IL)-6, C-reactive protein (CRP), and leukocyte counts and significantly decreased lymphocyte counts." (PMID 32443442, 2020). "Both IL-2R and IL-6 were statistically correlated with the severity of lung injury accessed by CT severity score and PaO2/FiO2 in COVID-19 patients with pneumonia." (PMID 32727465, 2020). "In this study, we identified an impaired type I IFN response in severe and critical COVID-19 patients, accompanied by high blood viral load and an excessive NF-κB–driven inflammatory response associated with increased TNF-α and IL-6." (PMID 32661059, 2020). "Monocytes and macrophages have an important role in respiratory failure during COVID-19; several studies have reported that these cells migrate to the lungs, producing pro-inflammatory cytokines, like IL-6, and inducing epithelial damage." (PMID 33193331, 2020). "Restoration of immune homeostasis, namely decreased IL-6 levels, is thought to be able to decrease the incidence of COVID-19 induced AKI and thus improves outcomes and survival." (PMID 32961074, 2020). "In vitro treatment with type IFNα restored type IFNγ secretion in COVID-19 patients while the secretion of pro-inflammatory cytokines IL6 and IL1β remained stable or decreased, respectively." (PMID 33585507, 2020). "Routine investigations proceeded with high-resolution computed tomography and IL-6 to monitor for progression to severe COVID-19." (PMID 33304877, 2020). "Based on multivariate analyses, decreased apoA-1 and HDL-C levels were independently associated with COVID-19 severity after adjusting for established indicators of severity, such as age, low albumin, and increased D-dimer, CRP, and IL-6 levels." (PMID 33344516, 2020). "In particular, significantly higher levels of IL-6 and IL-10 have been identified in severe COVID-19 patients than in the milder forms, thus suggesting that these cytokines can be used to predict the transition from mild to severe infection." (PMID 32397174, 2020). "Other therapeutic options targeting hyperinflammation, such as IL-6 blockade, are also being tested in COVID-19." (PMID 33298149, 2020). "For example, patients with severe COVID-19 had higher levels of IL-6, IL-2R, IL-10, and tumor necrosis factor alpha (TNF-α) than those with moderate disease, the former of which correlated with clinical severity and death." (PMID 33123165, 2020). "Serum profiling of COVID-19 patients has revealed a distinct inflammatory response characterized by high levels of interleukin-6 (IL-6) and reduced type I interferon." (PMID 32708264, 2020).
COVID-19 (continued). "In conclusion, our findings pointed to host sepsis as contributing to the extraordinary elevation of plasma IL-6 in critically ill patients with COVID-19." (PMID 32917983, 2020). "Clinical trials assessing the use of anti-IL-6 mAbs in COVID-19 patients indicate some improvement to clinical outcomes, but are limited in sample size and experimental design heterogeneity." (PMID 33510644, 2020). "Recently, two meta-analyses examining the role of IL-6 on COVID-19 concluded that IL-6 levels are significantly elevated in patients with COVID-19 and associated with adverse clinical outcomes." (PMID 32397399, 2020). "In keeping with these findings, blood IL-6 levels in COVID-19 patients on our clinical study decreased during acalabrutinib treatment (p=6.5E-4)." (PMID 32503877, 2020). "To verify IL-8 as an indicator of COVID-19 disease status, we measured IL-6 and IL-8 concentrations in the sera of 138 COVID-19 patients and 26 healthy people by ELISA assay." (PMID 33488599, 2020). "For patients with severe COVID-19, anti-IL-6 signaling agents displayed remarkable advantages in reducing mortality compared to SOC, consistent with the result above (pooled OR = 0.49, 95% CI 0.32–0.74, p = 0.0007)." (PMID 33384605, 2020). "This has resulted in the use of the IL-6 monoclonal antibody tocilizumab for the treatment of COVID-19." (PMID 33138181, 2020). "Tocilizumab (Actemra, Roche) is a humanized monoclonal antibody against the interleukin-6 receptor (IL-6R) approved for the treatment of seriously ill COVID-19 patients with elevated IL-6 by the National Health Commission of China." (PMID 33041830, 2020). "As observed in MERS, SARS-CoV-1, and COVID-19 patients it is understood that initially delayed but gradual increase in cytokines like IL-1β, IFN-γ, IL-6, IL-8, and IL-10 is the main cause of rapid sepsis progression." (PMID 33634060, 2020). "In line with the herein results, patients with COVID-19 treated with MSCs showed lower levels of TNFα, whereas they showed lower levels of IL-6 and higher levels of IL-10 in plasma/serum samples." (PMID 33634100, 2020). "Increased inflammation-related biomarkers were found in COVID-19 patients, including interleukin-6 (IL-6), C-reactive protein (CRP), ferroprotein, and so on." (PMID 33349241, 2020). "Other therapies that can be used to control the cardiovascular injury from COVID-19 are anti-viral agents, interleukin-6 inhibitors, and convalescent serum." (PMID 32670680, 2020). "IL-6 has been claimed to be crucially involved into the dysregulated host immune response of critically ill COVID-19 patients." (PMID 32774170, 2020). "Elevated plasma concentration of inflammatory mediators was observed in patients with COVID-19, including IL-6, IL-10, TNF-α, and other inflammatory cytokines, as well as ferritin and C-reactive protein." (PMID 33552062, 2020). "Massively elevated levels of IL-6 and a delayed cytotoxic immune defense characterized severe COVID-19-induced ARDS." (PMID 33123167, 2020). "COVID-19 patients showed that in the peripheral blood inflammatory cytokines such as, IL-2, IL-6, IL-10 and Tumor Necrosis Factor α (TNF-α) increased and CD4+, CD8+, CD16+, CD19+ and CD45+ T cells were decreased, but an increase in Th17 cell proportion." (PMID 32483409, 2020). "Aggressive tissue damage via increased IL-6 secretion and other cytokines leading to a hyper-inflammatory response are in line with COVID-19 disease severity." (PMID 33284859, 2020). "Coomes and his colleagues, in a recent systematic review and meta-analysis on the role of IL-6 in patients with COVID-19, showed that IL-6 was 2.9 times higher in patients with complicated COVID-19, compared with the non-complicated group." (PMID 32661796, 2020). "Inflammatory markers and cytokines, including C-reactive protein (CRP), ferritin, and interleukin (IL)-6, have been significantly elevated in multiple cohorts of patients infected with COVID-19." (PMID 32664919, 2020).
COVID-19 (continued). "It is important to note the effect of hUCESC reducing IL-6, as IL-6 has been proposed to be the main driver of the COVID-19 cytokine storm." (PMID 32766251, 2020). "Despite the numerous ongoing trials assessing the safety and efficacy of tocilizumab in COVID-19 patients, IL-6 play a role in controlling the lung inflammation and is important for the clearance of viruses." (PMID 33059757, 2020). "IL-6 can act on a large number of cells and tissues to get involved with the progression of COVID-19." (PMID 33195318, 2020). "A recent retrospective study involving 150 confirmed COVID-19 cases from Wuhan, China, revealed that elevated levels of serum ferritin and IL-6 were independent predictors of fatality, probably due to virally driven hyperinflammation." (PMID 33041830, 2020). "Comparison of hematological parameters between mild and severe cases of COVID-19 showed significant differences in interleukin-6 (IL-6), D-Dimer, glucose (GLU), thrombin time (TT), fibrinogen (FIB) and C-reactive protein (CRP)." (PMID 32259132, 2020). "Among severe COVID-19 cases, the majority of the patients with respiratory distress syndrome were associated with high systemic IL-1β, TNF-α, and IL-6 levels." (PMID 33488599, 2020). "Likely, the same processes occur in patients with COVID-19 and, thus, IL-6 overproduction mediates low HLA-DR expression on CD14+ monocytes." (PMID 32722596, 2020). "Neutralizing IL-6 or its receptor by using anti-IL-6 or anti-IL-6R antibodies, respectively, is being currently investigated to help severe cases of COVID-19 that suffer from complications derived from cytokine storm." (PMID 33324210, 2020). "Severe coronavirus disease 2019 (COVID-19) is characterized by the development of a deleterious hyperinflammatory response, in which the pleiotropic cytokine interleukin (IL)-6 plays a pivotal role." (PMID 33110739, 2020). "It is used for patients with severe COVID-19 and elevated IL-6 levels; the agent is being evaluated in a clinical trial." (PMID 32295188, 2020). "CRP is widely considered as a surrogate of IL-6 bioactivity and the role of IL-6 in inducing pro-inflammatory cytokines and the development of cytokine storm in COVID-19 patients indicates the importance of CRP in the assessment of the related complications." (PMID 32876941, 2020). "Apart from corticosteroids, IL-6 pathway inhibitors such as sarilumab, siltuximab and tocilizumab have been proposed as experimental approach considering the increased IL-6 levels that have been observed in patients with severe COVID-19." (PMID 32764417, 2020). "The role of IL-6 in COVID-19 patients has been highlighted in a recent retrospective multicenter study showing that circulating IL-6 levels were higher in COVID-19 deceased patients compared to discharged subjects." (PMID 32521760, 2020). "In Castleman disease, IL-6 is elevated in conjunction with TNFα, IL-1β and IL-10 as in severe COVID-19; however, vascular manifestations are unusual in this condition." (PMID 32629875, 2020). "IL-6 is one of the most reported cytokines in COVID-19 pathology, notably in severe patients exhibiting higher serum levels than mild cases." (PMID 32824753, 2020). "When compared to other causes of ARDS, COVID-19 patients with ARDS exhibited plasma IL-6 cytokine levels far below those exhibited in other non-COVID-19 ARDS patients." (PMID 33193418, 2020). "The mechanism of action is related to its capacity to inhibit IL-6, a pro-inflammatory cytokine, leading to a decrease in intensity of the inflammatory status developed by the critically ill COVID-19 patients." (PMID 32630746, 2020). "ACE2, and TMPRSS2 protease promote SARS-CoV-2 infectivity, while inflammatory cytokines IL-6, or G-CSF worsen COVID-19 severity." (PMID 33245731, 2020). "In later stages of COVID-19, the severity of the illness appears to be driven by the inappropriate release of several cytokines, such as IL-6 and GM-CSF." (PMID 32719685, 2020).
COVID-19 (continued). "In COVID-19, IL-6 inhibitors should be carefully administered with appropriate timing due to its control of viral replication." (PMID 33194450, 2020). "In the IL6 gene, the rs1800795 SNP showed a weak correlation (r2 = 0.0136, p = 0.8260) with the case fatality rate of COVID-19." (PMID 33396837, 2020). "Among cytokines, elevated levels of IL-6 have been consistently reported in several COVID-19 patient cohorts, correlates with disease activity, and with lymphopenia and low NK cells counts." (PMID 33370397, 2020). "Two hallmarks of severe COVID-19 are hyperinflammation, most typically involving a “cytokine storm” with massive interleukin 6 (IL6) expression, and hyperferritinemia." (PMID 33087116, 2020). "CXCL10 (IP-10), IL-8, and IL-6 were elevated in acute COVID-19 (p < 0.0001, p < 0.05, p < 0.001) and correlated with disease severity, consistent with large cohort studies of plasma cytokines." (PMID 33010815, 2020). "Tissue damage in COVID-19 is mainly mediated by an excess of immune response to the virus, which results in a cytokine storm, with activation of the IL-6 signaling pathway." (PMID 33159214, 2020). "As such, more studies are needed to clarify the possible modulatory effect exerted by IL-6 antagonism in COVID-19 patients, and its impact on the intersecting pathways leading to respiratory and cardiovascular complications." (PMID 32581799, 2020). "Our analysis focused on detecting statistical differences in levels of 6 cytokines associated with cytokine storm (IL-1β, IL-1RA, IL-6, IL-8, IL-18, and TNF-α) between patients with moderate COVID-19, severe COVID-19, and ARDS or sepsis." (PMID 32706339, 2020). "It has been reported that IL-6 was significantly increased in severe COVID-19 cases, and its level was closely correlated with the severity of patients." (PMID 32708495, 2020). "The potential risk factors of males, older age, with comorbidities, low T lymphocyte level and high level of NLR, CRP, IL-6 can help to predict clinical progression of COVID-19 at an early stage." (PMID 32620125, 2020). "COVID-19 patients with myocardial injury showed markedly increased levels of interleukin-6 [6.5 (5.2–17.9) vs. 2.3 (1.5–6.3) pg/mL; P < 0.001]." (PMID 33505992, 2020). "In the current study, the cytokine examination of cancer patients showed significantly elevated levels of the IL-2 receptor and IL-6 in COVID-19 patients with cancer." (PMID 32522278, 2020). "Other sources have proposed the interleukin (IL)-6 inhibitor tocilizumab as a potential treatment for COVID-19, and due to its modulator effect on IL-6, cholecalciferol has again been postulated as a potential therapeutic option." (PMID 33322317, 2020). "Serum levels of IL-8 correlated better than IL-6 levels with the overall clinical disease scores at different stages of the same COVID-19 patients." (PMID 33488599, 2020). "Both studies suggest that IL-6 and IL-10 are predictive factors of COVID-19 severity and progression." (PMID 33584667, 2020). "Increased levels of proinflammatory cytokines, particularly interleukin 6, have been described among patients with severe COVID-19." (PMID 32938419, 2020). "The fact that microdose lithium suppresses IL-6 and recent finding correlating IL-6 level with severity of the diseases in COVID-19 patients provides a strong rationale for why lithium treatment should be tested as treatment." (PMID 32534451, 2020). "A majority of patients with COVID-19 exhibit a predominant IL-1/IL-6 signature, but can evolve into an IL-18/IFNγ signature mimicking cytokine profiles observed in other inflammatory diseases such as macrophage activation syndrome (MAS)." (PMID 32699149, 2020). "Given the poor clinical outcomes of severe COVID-19 patients despite their relatively lower levels of IL-6, it is noteworthy that COVID-19 ARDS patients exhibit severe endotheliopathy in the lungs, including the presence of microthrombi." (PMID 32826331, 2020).